USP22 (ubiquitin specific peptidase 22)
Diseases named in the same sentence as USP22 in open-access papers (continued):
Sharing a sentence is not in itself a finding about the gene and the disease.
diabetic kidney disease (4 papers, 2017 to 2026). Progressive kidney disorder caused by vascular damage to the glomerular capillaries, in patients with diabetes mellitus. "USP22 in podocytes promotes diabetic nephropathy by enhancing oxidative stress, while USP22 in mesangial cells suppresses fibrosis through the stabilization of Sirt-1." (PMID 36834633, 2023). "Further studies are required to address the discrepancies regarding USP22 function in diabetic nephropathy." (PMID 36834633, 2023). "In contrast to the beneficial roles of USP22 in diabetic nephropathy, some reports have indicated the detrimental effects of USP22 in similar models." (PMID 36834633, 2023). "USP9X in renal epithelial cells, and USP22 in renal epithelial cells and mesangial cells have beneficial effects on diabetic nephropathy." (PMID 36834633, 2023). "Therefore, USP22 signaling in mesangial cells has beneficial effects on the pathogenesis of diabetic nephropathy via Sirt-1 stabilization." (PMID 36834633, 2023). "Some studies have also highlighted the significant role of USP22 in diabetic nephropathy." (PMID 36834633, 2023). "The deubiquitinating enzymes UCH-L1, USP22, OTUD5, and USP14 act on PIRK3, TAK1, and SPAG5, respectively, and play a regulatory role in the pathophysiological process of diabetic kidney disease." (PMID 40225869, 2025).
oral squamous cell carcinoma (4 papers, 2012 to 2024). "The aim of this study was to investigate the role of USP22 and the association with its potential targets in oral squamous cell carcinoma (OSCC)." (PMID 22880026, 2012). "However, clinicopathologic significance of USP22 in oral squamous cell carcinoma (OSCC) has not yet been elucidated." (PMID 22880026, 2012).
anaplastic thyroid carcinoma (3 papers, 2016 to 2019). "USP22 knockdown in anaplastic thyroid carcinoma cells induces mitochondria-dependent apoptotic pathway by upregulating levels of apoptotic protein, Bax and Bid, and activating caspase-3." (PMID 31689236, 2019). "Ubiquitin-specific protease 22 (USP22) aberrance has been implicated in several malignancies; however, whether USP22 plays a role in anaplastic thyroid carcinoma (ATC) remains unclear." (PMID 27145278, 2016).
cervical cancer (3 papers, 2018 to 2024). A primary or metastatic malignant neoplasm involving the cervix. "In this study, we employed chromatin immunoprecipitation sequencing (ChIP-seq)technology to study the potential targets of USP22 in human cervical cancer cells.Furthermore, we explored transcriptome profiling in response to USP22 silencing." (PMID 30088609, 2018).
cholangiocarcinoma (3 papers, 2021 to 2025). A carcinoma that arises from the intrahepatic biliary tree (intrahepatic cholangiocarcinoma) or from the junction, or adjacent to the junction, of the right and left hepatic ducts (hilar cholangiocarcinoma). "In 2021, Tian and colleagues elucidated the critical role of USP22 in promoting cholangiocarcinoma invasion and identified its associated molecular mechanisms." (PMID 41301681, 2025). "This review synthesizes current knowledge on six USP members—USP1, USP3, USP8, USP9X, USP21, and USP22—and delineates their context-dependent roles across cholangiocarcinoma and GBC subtypes." (PMID 41301681, 2025). "Oncogenic ubiquitin-specific protease 22 (USP22) is implicated in a variety of tumours; however, evidence of its role and underlying molecular mechanisms in cholangiocarcinoma (CCA) development remains unknown." (PMID 34226501, 2021).
myeloproliferative neoplasm (3 papers, 2022 to 2024). A clonal hematopoietic stem cell disorder, characterized by proliferation in the bone marrow of one or more of the myeloid (i.e., granulocytic, erythroid, megakaryocytic, and mast cell) lineages. "Expression level of PU.1 was decreased in USP22-deficient KRAS-induced myeloproliferative neoplasm mice (KMUKO) as compared to the KRAS-induced myeloproliferative neoplasm mice (KM)." (PMID 35008940, 2022). "However, in myeloproliferative neoplasms (MPNs) driven by oncogenic conditions Kras mutation, loss of USP22 results in myeloid leukemia." (PMID 35935969, 2022).
myocardial ischemia (3 papers, 2022 to 2025). A disorder of cardiac function caused by insufficient blood flow to the muscle tissue of the heart. "Recent research has shown that USP22 protects against myocardial ischemia‒reperfusion injury, but it is still unknown how USP22 affects Ang II-induced cardiac remodeling and hypertrophy." (PMID 37324479, 2023).
nasopharyngeal carcinoma (3 papers, 2021). A carcinoma arising from the nasopharyngeal epithelium. "miR-30e-5p inhibits the proliferation and metastasis of nasopharyngeal carcinoma cells by targeting USP22." (PMID 34336826, 2021). "MiR-30e-5p targets USP22 to suppress the proliferation of nasopharyngeal carcinoma cells." (PMID 33568633, 2021).
retinoblastoma (3 papers, 2021 to 2022). A malignant tumor that originates in the nuclear layer of the retina.
acute promyelocytic leukemia (2 papers, 2021 to 2024). An aggressive form of acute myeloid leukemia (AML), characterized by arrest of leukocyte differentiation at the promyelocyte stage, due to a specific chromosomal translocation t(15;17) in myeloid cells. "On the other hand and in agreement with USP22 KO HT‐29, USP22 KO Jurkat ALL were not sensitized for TB‐induced cell death, compared to control Jurkat (Fig EV1G–I), similar as USP22 KO acute promyelocytic leukemia (APL) NB4 cells." (PMID 33369872, 2021). "Here, we identify USP22 as regulator of PML and the oncogenic acute promyelocytic leukemia (APL) fusion PML-RARα protein stability and identify a destabilizing role of PML residue K394." (PMID 38467608, 2024).
autoimmune disease (2 papers, 2018 to 2023). A disorder resulting from loss of function or tissue destruction of an organ or multiple organs, arising from humoral or cellular immune responses of the individual to their own tissue constituents. "Nevertheless, as Usp22 deletion in vivo caused strong defects in various Ig isotypes but less so to IgA, Usp22 could be exploited as a therapeutic target in IgG or IgE-mediated autoimmune diseases, such as systemic lupus erythematosus, autoimmune thrombocytopenia, and asthma." (PMID 29520062, 2018). "It is expected that Usp22 inhibitors have the potential of ameliorating the pathogenesis of these antibody-mediated autoimmune diseases, without disturbing the homeostasis of the gut microbiota." (PMID 29520062, 2018).
brain glioma (2 papers, 2017 to 2023). A malignant glioma that involves the brain. "For example, USP22 silencing in brain glioma cell lines was associated with reduced CDK1 and Cyclin B1 expression, two proteins required for mitosis initiation and progression, and induced a G2/M arrest." (PMID 29210986, 2017). "Multiple studies show that USP22 silencing increases apoptosis in both mouse and human embryonic fibroblasts, as well as in multiple cancer cell lines, including colorectal and brain glioma cell lines." (PMID 29210986, 2017).
carcinomas of salivary duct (2 papers, 2014 to 2021). "Recent studies showed that increase expression of USP22 in salivary duct carcinoma patients were associated with a poor prognosis." (PMID 24466336, 2014). "USP22 overexpression is correlated with poor clinical outcomes in carcinomas of salivary duct, esophageal squamous cell and liver." (PMID 34226501, 2021). "To date, several studies have reported USP22 was predicted as a poor prognostic factor in patients with non-small cell lung cancer, salivary duct carcinoma, papillary thyroid carcinoma and oral squamous cell carcinoma." (PMID 24466336, 2014).
colorectal tumor (2 papers, 2019 to 2021). "In summary, Apc-mutated mice with an intestinal deletion of Usp22 displayed increased colorectal tumor burden, immune cell infiltration and increased bone fragility." (PMID 33920268, 2021). "In addition, Usp22 deletion resulted in increased inflammation-associated colorectal tumor growth." (PMID 33920268, 2021). "In addition, simultaneous Apc mutation and intestinal Usp22 knockout in a model for inflammation-associated CRC resulted in decreased survival and increased colorectal tumor burden." (PMID 33920268, 2021).
Hyperglycemia (2 papers, 2023 to 2025). An increased concentration of glucose in the blood. "Hyperglycemia has been shown to decrease intracellular USP22, which stabilizes Sirt-1 through direct interactions." (PMID 36834633, 2023). "USP22 in pancreatic β-cells, USP2 in adipose tissue macrophages, USP9X, 20, and 33 in myocytes, USP4, 7, 10, and 18 in hepatocytes, and USP2 in hypothalamus improve hyperglycemia, whereas USP19 in adipocytes, USP21 in myocytes, and USP2, 14, and 20 in hepatocytes promote hyperglycemia." (PMID 36834633, 2023).
leukemia (2 papers, 2021 to 2024). A malignant (clonal) hematologic disorder, involving hematopoietic stem cells and characterized by the presence of primitive or atypical myeloid or lymphoid cells in the bone marrow and the blood. "However, to date, in vivo genetic mouse model studies examining the role of USP22 in cancer have been limited to prostate, leukemia, and colorectal malignancies." (PMID 34007022, 2021). "Our findings imply USP22-dependent surveillance of PML-RARα stability and IFN signaling as important regulator of APL pathogenesis, with implications for viral mimicry, differentiation and cell fate regulation in other leukemia subtypes." (PMID 38467608, 2024). "Along with recent findings on enhanced IFN type I and III responses during viral defense in the absence of USP22, USP22 is revealed as major regulator of IFN signaling in human leukemia." (PMID 38467608, 2024).
myeloid leukemia (2 papers, 2019 to 2023). A clonal proliferation of myeloid cells and their precursors in the bone marrow, peripheral blood, and spleen. "Surprisingly, a very recent study demonstrated that USP22 deficiency leads to myeloid leukemia upon oncogenic KRAS activation through a PU.1 dependent mechanism." (PMID 31842906, 2019). "On the other hand, USP22 deficiency decreases PU.1 stability to promote myeloid leukemia." (PMID 36906615, 2023).
prostate adenocarcinoma (2 papers, 2014 to 2017). "USP22 controls androgen receptor (AR) accumulation and signaling, and is a predictor of androgen deprivation therapy in prostate adenocarcinoma." (PMID 28567015, 2017).
renal cell carcinoma (2 papers, 2022 to 2024). "In hepatocellular and renal cell carcinoma however, USP22 deficiency has been reported to enhance caspase-3 activation, emphasizing the need for further investigations." (PMID 38467608, 2024). "For instance, USP22 enhanced cell proliferation via increasing surviving stability in renal cell carcinoma (RCC) cells." (PMID 35692754, 2022).
Acute hepatitis (1 paper, 2023). Acute hepatic injury resulting from inflammation typically accompanied by increased serum alanine transaminase activity. "Similarly, in our research work, acute hepatitis in Usp22 deficient mice resulted from immunopathology directed by uncontrolled activation of CD8+ T cells following activation of myelomonocytic cells that initiated liver damage." (PMID 37896966, 2023).
acute liver failure (1 paper, 2023). Rapid deterioration of liver function causing encephalopathy and coagulopathy. "Ablation of CD8+ T cells restricted immunopathology in the liver due to LCMV infection in Usp22 KO mice, whereas depletion of granulocytes and monocytes only prolonged the time until the appearance of acute liver failure." (PMID 37896966, 2023).
acute lymphoblastic leukemia (1 paper, 2021). Leukemia with an acute onset, characterized by the presence of lymphoblasts in the bone marrow and the peripheral blood. "Importantly, apart from HT‐29, loss of USP22 expression in the human acute lymphoblastic leukemia (ALL) Jurkat cell line also prominently reduced TBZ‐induced necroptosis, compared to control Jurkat cells (Fig EV1G–I)." (PMID 33369872, 2021).
adenoma (1 paper, 2022). A neoplasm arising from the epithelium. "Interestingly, the expression of USP22 was not significantly upregulated from normal tissues to adenomas, suggesting that USP22 activation is enhanced during colorectal carcinogenesis." (PMID 35935969, 2022).
Autoimmunity (1 paper, 2023). The occurrence of an immune reaction against the organism's own cells or tissues. "That means, that the lack of Usp22 might be responsible for the disturbed function of regulatory T cells supporting the trends toward autoimmunity in Usp22 deficient mice." (PMID 37896966, 2023). "The observations from our in vivo experiments in the Usp22 KO mouse model upon LCMV infection support the idea of the Usp22 absence as a stimulator of proinflammatory signaling and innate immune response, probably serving as a trigger of autoimmunity." (PMID 37896966, 2023).
bladder tumors (1 paper, 2011).
cardiac hypertrophy (1 paper, 2023). "However, the molecular processes underlying the functions of USP22 and Sirt1 in Ang II-induced ventricular hypertrophy are unknown." (PMID 37324479, 2023). "In this study, we used FO as a protective agent to investigate its effects on USP22/Sirt 1 in Ang II-induced cardiac hypertrophy and aimed to highlight a novel targeted approach to treat heart failure." (PMID 37324479, 2023). "In the current study, we show that the overexpression of USP22 induced by treatment with FO greatly improved Ang II-induced cardiac dysfunction, heart hypertrophy, inflammation, and fibrosis." (PMID 37324479, 2023). "The role of USP22 in Ang II-induced cardiac hypertrophy and the oxidative response was then investigated." (PMID 37324479, 2023). "However, treatment with FO significantly upregulated the expression of USP22 and reduced the incidence of cardiac hypertrophy, fibrosis, inflammation, and oxidative responses." (PMID 37324479, 2023).
chronic periodontitis (1 paper, 2026). A chronic inflammatory process that affects the tissues that surround and support the teeth. "Endothelial-specific inhibition of USP22 alleviates BBB dysfunction and central inflammatory responses, highlighting USP22 as a potential therapeutic target for neuroinflammatory disorders associated with chronic periodontitis." (PMID 41908490, 2026).
epilepsy (1 paper, 2021). A brain disorder characterized by episodes of abnormally increased neuronal discharge resulting in transient episodes of sensory or motor neurological dysfunction, or psychic dysfunction. "Interestingly, we observed that when compared to the normal controls, the expression of some identified genes was only significantly altered either in Epilepsy (EGLN1, ELAVL4, and NFE2l2) or Hemorrhage (USP22, EYA1, SIX1, OAS3, SRMS) groups." (PMID 34588521, 2021).
esophageal squamous cell carcinoma (1 paper, 2014). Esophageal squamous cell carcinoma (ESCC) is a type of esophageal carcinoma (EC) that can affect any part of the esophagus, but is usually located in the upper or middle third. "USP22 are found significantly associated with progression and unfavorable clinical outcome in esophageal squamous cell carcinoma, NSCLC." (PMID 24997798, 2014).
gastric adenocarcinoma (1 paper, 2020). "Compared with that in normal gastric tissue, the mRNA expression of USP22 in gastrointestinal stromal tumor samples was significantly increased, whereas the mRNA expression of USP22 in gastric adenocarcinoma tissue was slightly increased without statistical significance." (PMID 32063746, 2020). "However, the mRNA expression of USP22 in gastric adenocarcinoma tissue was slightly increased without statistical significance." (PMID 32063746, 2020).
gastrointestinal stromal tumor (1 paper, 2020). "By analyzing the mRNA expression data from the TCGA database, we found that the mRNA expression of USP22 in gastrointestinal stromal tumor samples was significantly increased compared with that in normal gastric tissue." (PMID 32063746, 2020).
ischemia (1 paper, 2025). A hypoperfusion of the BLOOD through an organ or tissue caused by a PATHOLOGIC CONSTRICTION or obstruction of its BLOOD VESSELS, or an absence of BLOOD CIRCULATION.
lentivirus infection (1 paper, 2023). Virus diseases caused by the Lentivirus genus. "To further investigate the effect of USP22 on HCC progression, we first generated Huh7 cells and PLC/PRF/5 cells with stable knockdown of USP22 (shUSP22) by lentivirus infection, a scramble shRNA as a control (shCtrl) as indicated." (PMID 36906615, 2023). "To examine whether USP22 affected the histone H2Bub or ZEB1 recruitment to the VEGFA-promoter I region, we first constructed HCCLM3 cell lines with stable knockdown of USP22 (shUSP22) by lentivirus infection, a scramble shRNA as a control (shCtrl)." (PMID 36906615, 2023).
lipodystrophy (1 paper, 2024). A congenital or acquired disorder characterized by abnormal loss or redistribution of the adipose tissue in the body. "Impairment of USP22 functions upon loss of SAGA integrity might also be related to the intrauterine retardation observed in the SUPT7L deficient lipodystrophy patient, as USP22 is required for placental vasculogenesis in mice." (PMID 39222683, 2024).
liver failure (1 paper, 2023). A liver disease characterized by the liver losing or has lost all of its function. "There, the occurrence of liver failure after LCMV infection in Usp22 KO mice was successfully prevented by the treatment with a monoclonal anti-CD8+ T cell antibody." (PMID 37896966, 2023). "Thus, the onset of liver failure due to LCMV infection was delayed but not abrogated in Usp22 KO mice that received treatment with anti-Gr-1 antibody." (PMID 37896966, 2023).
metastatic cancers (1 paper, 2019). A carcinoma which has spread from the original site of growth to another anatomic site. "The Kaplan-Meier analysis shows that USP22 knockout significantly prolonged survival of metastatic cancer-bearing mice (P < 0.0001)." (PMID 31842906, 2019). "Compared with the metastatic cancer nodules (having a clear boundary) formed by H1299 cancer cells (5–8 large nodules/each), the metastatic cancer nodules formed by USP22−/− H1299 cancer cells were much less abundant and smaller (1–3 small nodules/each)." (PMID 31842906, 2019). "Notably, USP22 knockout dramatically suppressed in vitro proliferation, colony formation; and angiogenesis, growth, metastasis of A549 and H1299 in mouse xenograft model, and significantly prolonged survival of metastatic cancer-bearing mice." (PMID 31842906, 2019). "Therefore, all data demonstrated that USP22 knockout significantly suppressed metastasis of NSCLC, and prolonged survival of metastatic cancer-bearing mice." (PMID 31842906, 2019).